CCR2 (C-C motif chemokine receptor 2)
Diseases named in the same sentence as CCR2 in open-access papers (continued):
Sharing a sentence is not in itself a finding about the gene and the disease.
tumor (continued). "Our flow cytometry analysis data indicated that these FAP+CD45+ cells were likely myeloid cells, consistent with previous work demonstrating that macrophages, specifically F4/80high/CCR2+/CD206+ M2 or tumor-associated macrophages (TAMs), express FAP." (PMID 38275890, 2024). "Initial transcriptional and functional studies revealed that metastasis-associated macrophages are distinct from primary tumor TAMs and express markers associated with inflammatory monocytes and macrophages and the chemokine receptor CCR2." (PMID 39402303, 2024). "The CCL2/CCR2 axis plays multiple protumorigenic roles and is implicated in cancer formation and metastasis, tumor cell invasion and the promotion of angiogenesis." (PMID 39457710, 2024). "A comparative study of murine glioma synthesized CCL2 was reported to facilitate the recruitment of CCR2+ Ly6C+ monocytic MDSCs (M-MDSCs) to the tumor site, while CCL2-deficient tumor site witnessed a significant reduction in MDSCs infiltration." (PMID 38360737, 2024). "In cancer studies, beta chemokines have been shown to play a protumorogenic role by recruiting CCR2+ monocytes to the tumor site, which subsequently differentiate into tumor-associated macrophages (TAMs)." (PMID 39594640, 2024). "CCL2 facilitates the polarization of macrophages towards the M2 phenotype, which is associated with tumor growth stimulation by engaging the CC2 chemokine receptor (CCR2) from the macrophage surface." (PMID 39457618, 2024). "The activation of the CCL2/CCR2 axis, which mediates the crosstalk between tumor-associated macrophages (TAMs) and tumor cells, is associated with angiogenesis, metastases, immunosuppression, and cancer progression." (PMID 37626858, 2023). "PEGylated NOX-E36 binds the chemokine CCL2 thereby preventing the infiltration of CCR2-dependent tumor associated macrophages that initiate tumor-supporting angiogenesis." (PMID 36798121, 2023). "The abundance of CCR2+ monocytes in the TME is associated with the suppression of T cells in various cancer models shaping tumor progression because of immunosuppressive mechanisms initiated upon recruitment." (PMID 37849753, 2023). "Monocyte mobilization from the bone marrow to PDAC appears to be driven by the CCL2/CCR2 chemokine axis, ultimately leading to their differentiation into tumor-associated macrophages (TAMs)." (PMID 37509365, 2023). "It is also accompanied by evidence that the tumor-promoting properties of CA-MSCs have been attenuated in CCR2-deficient mice." (PMID 38022534, 2023). "The impact of CCR2 deficiency on tumor growth, T-cell infiltration, proliferation, apoptosis, or angiogenesis was heterogeneous." (PMID 37208442, 2023). "In line with this, the observed CCR2+ monocytes expressed Irf8, which is associated with the induction of T cell exhaustion, further promoting tumor growth." (PMID 37849753, 2023). "Cysteine‒cysteine chemokine receptor type 2 (CCR2) is expressed by tumor-infiltrating myeloid cells, including tumor-associated macrophages (TAMs), and promotes immune escape by limiting CD8+ T-cell infiltration." (PMID 37354378, 2023). "Here, while they achieved a decrease of CD14+CCR2+ inflammatory monocytes in the peripheral blood samples, only 2 of 21 patients had a decrease CCR2+ tumor associated macrophages." (PMID 37181043, 2023). "Tumor-associated macrophages (TAMs) crosstalk with LC cells via the C-C chemokine receptor type-2 (CCR2) and CX3C chemokine receptor 1 (CX3CR1)." (PMID 36618350, 2022). "For example, PDAC cells use the CCL2/CCR2 axis to recruit tumor-associated macrophages (TAMs) and myeloid-derived suppressor cells (MDSCs), and the CCL5/CCR5 axis to recruit regulatory T cells (Tregs)." (PMID 35205732, 2022). "Acceleration of tumor growth was associated with increased CCR2+ Ly-6Chi monocyte levels in blood and early recruitment into the tumors." (PMID 36104342, 2022).
tumor (continued). "In mouse models, inhibiting CCR2 and CSF-1R can antagonize the ability of tumor-associated macrophages to suppress T cell responses." (PMID 36143975, 2022). "The combination of RT + αPD-1 + CCR2/5i enhanced intratumoral effector and memory T cell infiltration but suppressed regulatory T cell, M2-like tumor–associated macrophage, and myeloid-derived suppressive cell infiltration." (PMID 35404390, 2022). "For example, PF-04136309, a small molecule CCR2 inhibitor, inhibits tumor-associated macrophage infiltration and enhances endogenous anti-tumor immunity, and has performed well in clinical studies for advanced pancreatic cancer." (PMID 36313280, 2022). "The expression of CXCR3 on malignant tumor cells has been correlated to increased tumor growth and spread, while CCR2 participates in tumor metastasis by promoting the trafficking of tumor associated macrophages into the TME with consequent angiogenesis." (PMID 34869014, 2021). "Tumor-associated M2 polarized macrophages (TAMs) promote tumor cell to bone metastasis through CCL2/CCR2 or colony-stimulating factor 1 (CSF1)/CSF1R signaling." (PMID 34831167, 2021). "Targeting CCR2 also reduces tumor progression associated with an influx of T cells in preclinical glioma and pancreatic models." (PMID 33953710, 2021). "In a mouse with pancreatic cancer, using a CCR2 antagonist was associated with significant inhibition of macrophage infiltration into the tumor region." (PMID 34394072, 2021). "The involvement of CCL2 in the recruitment of CCR2-bearing tumor-associated macrophages (TAMs), which play critical roles in tumor vascularization and development, has been widely explored." (PMID 34943797, 2021). "Administration of a CCR2 antagonist or the loss of CCL2 expression in tumor cells enhances antitumor immunity in the residual tumor and overcomes the resistance to ICB therapy." (PMID 35003065, 2021). "The intestinal microbial imbalance caused by HFD mediates the activation of the MCP-1/CCR2 axis, recruits monocytes to the tumor microenvironment and promotes polarization to TAMs, thereby altering the tumor immune microenvironment." (PMID 33897888, 2021). "Neutralization of CCL2 or CCR2 deficiency blocks monocyte recruitment, reduces MØs interacting with tumor cells and more importantly reduces lung metastasis." (PMID 34804061, 2021). "It has been shown that tumor‐associated macrophages derived from circulating CCR2+ bone‐derived monocytes." (PMID 34633664, 2021). "CCR2 inhibition decreases tumor-associated MDSCs and thus unmasks an anti-PD-1 survival benefit to slow the progression of resistant murine gliomas." (PMID 35003065, 2021). "To explicate the mechanism underlying tumor promotive function of infiltrated TAMs, we carried out RNA-sequencing with tumors harvested from the CCR2−/− mouse model." (PMID 32103760, 2020). "In this scenario, the CCL2/CCR2 axis is attracting particular interest and plays multiple important roles in systemic tumor-associated myeloid cell responses." (PMID 32582203, 2020). "Along the same lines, a subset of CCR2+ myeloid cells has also been associated with primary tumor recurrence, or re-fertilizing the soil for any remaining local or circulating tumor cells to grow." (PMID 32983100, 2020). "In the mouse model, VEGFR1+CCR2+CX3CR1+Tie2–CXCR4− macrophages were associated with tumor cell seeding." (PMID 32726950, 2020). "For example, in Ccr2-/- mice engrafted with colorectal cancer, reduction in monocyte-derived TAMs was associated with reduced tumor burden suggesting a role of mo-TAMs in tumor growth." (PMID 32509781, 2020). "Macrophages can be converted to TAM within the tumor by secreted factors, such as c-c chemokine receptor type-2 (CCR2), which causes them to exhibit an M2-like phenotype; this conversion of macrophages leads to a distinct subpopulation." (PMID 30701168, 2019).
tumor (continued). "In a co-graft tumour model, fibroblast-derived MCP-1 attenuated the effect of an MCP-1-neutralising antibody, while mutation of CCR2 in cancer cells significantly reduced tumour growth, indicating MCP-1 involvement in basal-like cell cancer progression." (PMID 31713180, 2019). "A particularly interesting Phase Ib trial investigated an oral CCR-2 inhibitor (PF-04136309), a strategy aimed to target CCL2-CCR2 chemokine signaling that mediates tumor-associated macrophage recruitment, and therefore restores anti-tumor immunity." (PMID 29765563, 2018). "We have utilized transplantable lung tumor cell line (TC1) to address the role of the CCR2/MCP-1 axis in MDSC associated tumor progression." (PMID 30400822, 2018). "Chemokine CCL2 binding to CCR2, its cognate receptor, elicits the recruitment of monocytes and tumor-associated macrophages (TAMs) into the tumor microenvironment." (PMID 29891787, 2018). "On the other hand, CCR2+ myeloid cells have been implicated in promoting an immunosuppressive tumor environment." (PMID 28844797, 2017). "Blockade of CCL2/CCR2 is associated with reduced influx of inflammatory monocytes and tumour associated macrophages into HCC microenvironment." (PMID 27270308, 2016). "The impact ranitidine had in decreasing E0771 tumor growth was CCR2-dependent and therefore potentially linked to monocyte recruitment." (PMID 26863636, 2016). "Inhibition of monocyte recruitment, through CCR2 deficiency, prevents the action of ranitidine in reducing tumor growth." (PMID 26863636, 2016). "FSTL1 can confer bone polarity on tumor cells by inducing the bone metastasis-associated molecular expression such as CCR2, CXCR4, and RANKL." (PMID 25883937, 2015). "Mouse T cell surface marker CD3 epsilon chain (CD3e) and CD8 alpha chain (CD8a) were chosen as test criteria for tumor-infiltrating lymphocytes, while IFNγRβ, CCR2, IL-2Rα and CCR5 were chosen as Th1-associated markers." (PMID 26417929, 2015). "The CCL2/CCR2 signaling axis has recently been implicated in tumor development, suggesting endothelial expression of CCR2 to increase vascular permeability and responsiveness to CCL2 positive monocyte infiltration." (PMID 25909848, 2015). "Our data indicate that silibinin decreases CCR2 expression in MDSCs, thus providing a mechanism for the decreased accumulation of MDSCs in the tumor that results in a decrease in tumor-associated immunosuppression." (PMID 24574320, 2014). "The increased stability of CCR2A due to CCR2-64I variant sustains the tumours by continuously recruiting TAMs that support tumour angiogenesis." (PMID 20537184, 2010). "CCR2 antagonists such as PF-04136309 have been shown to reduce tumor-associated macrophage infiltration and enhance antitumor immunity in pancreatic ductal adenocarcinoma, leading to improved tumor control in combination with chemotherapy." (PMID 41002423, 2025). "Whereas naïve lung and blood mostly contained differentiated NK cells, metastatic lungs harbored a large cluster of tumor-associated NK cells (Tumor NK) expressing markers of less differentiated NK cells (Emb, Cd27, Ccr2, Cd28, Thy1 or Sell), confirming our flow cytometric data." (PMID 41145419, 2025). "Collectively, these data reveal that CCR2 is highly expressed in intratumoral myeloid cells on the majority of primary NSCLC, PDACs, and CRCs and that high CCR2 is associated with enhanced local adaptive immune responses and specific clinical and molecular tumor subsets." (PMID 39918395, 2025). "However, an increase in tumor-associated CXCR2+ neutrophils compensated for the beneficial effects of CCR2+ macrophage-targeted therapy; therefore, targeting both myeloid cell types appears to be critical to improve response to chemotherapy." (PMID 40917508, 2025). "Also co-depletion of CXCR2+ tumor-associated neutrophils overcomes the compensatory response of neutrophil mobilization by depletion of CCR2+ tumor-associated macrophages." (PMID 40050933, 2025).
tumor (continued). "However, CCR2 deficiency alone was insufficient for significant tumor regression but proved more effective when combined with checkpoint inhibitors." (PMID 40281508, 2025). "Similarly, the blockade of CCR2 restored anti-tumour immunity in the preclinical pancreatic ductal adenocarcinoma by decreasing the number of tumour associated macrophages." (PMID 40852716, 2025). "Therefore, in myeloid cells, PEFs primarily modulate MDSCs through the NLRP3/IL-1β signaling pathway and regulate tumor-associated macrophages via the CCLs/CCR2 signaling axis." (PMID 41357174, 2025). "This study used an orthotopic lymph node metastasis model in mice and found that tumor-associated macrophages (TAMs) infiltrated into lymph node sinuses secreted a large amount of CCL-2 in an autocrine or paracrine manner to induce CCR-2-positive tumor cells metastasize to lymph nodes." (PMID 39328205, 2024). "CCR2 is closely linked to tumor-related inflammation and can accelerate tumor growth." (PMID 39575419, 2024). "To test whether CCR2 deficiency impaired migration of I-NCMs into tumor colonies, we used Ccr2RFP/RFP mice, in which the knockin of RFP precluded Ccr2 transcription, or Ccr2RFP/+ control mice." (PMID 39545417, 2024). "Additionally, EHF proficiently recruits and activates tumor‐associated macrophages via the CCL2/CCR2 axis, leading to tumor microenvironment remodeling." (PMID 38741887, 2024). "Similarly, CCR2 expression has been implicated in promoting tumour cell survival, proliferation, and metastasis, contributing to treatment resistance and poor prognosis in CRPC." (PMID 39199567, 2024). "Moreover, blocking the CCL2/CCR2 pathway prevents the recruitment and infiltration of inflammatory monocytes and the M2 polarization of tumor-associated macrophages (TAMs)." (PMID 39199602, 2024). "made a significant finding demonstrating that targeting the CCL2/CCR2 axis therapeutically could effectively impede the recruitment of inflammatory monocytes, inhibit tumor-associated macrophage (TAM) infiltration, and reverse M2 polarization." (PMID 38274805, 2023). "CCL2 released by tumor cells, endothelial cells, fibroblasts, and Schwann cells through engaging with its receptor CCR2 is able to regulate the infiltration and migration of tumor-associated macrophages, which facilitate tumor growth by inducing immune suppression." (PMID 37404751, 2023). "The associated tumor growth could only be slowed down temporarily by the anti-CCR2 antibody MC-21, demonstrating the need for alternative substances to permanently deplete tumor-promoting monocytes." (PMID 37849753, 2023). "In established tumors, classic Ly6C+ monocytes migrate to tumors in a C-C chemokine receptor-2 (CCR2)-dependent manner and mainly differentiate into tumor-associated macrophages, which contribute to tumor progression, metastasis formation and therapy resistance." (PMID 36792589, 2023). "Importantly, CCR2 inhibitors also partially reversed the increase in tumor growth and alleviated the weight loss caused by FAM171B overexpression." (PMID 37915048, 2023). "It is noted that CCR2+ monocytes/macrophages have been linked to tumor metastasis and progression." (PMID 35140221, 2022). "Finally, in HNSCC, tumor progression has been associated with an increased detection of CCR2+ TA-Tregs." (PMID 33924428, 2021). "Additionally, TAMs from tumor-bearing CCR2 knockout mice expressed a reduced amount of Vegf, and the tumor vasculature was less leaky and more mature, underlining the importance of CCR2 signaling in GBM angiogenesis." (PMID 34203660, 2021). "However, in CCR2-DTR PyMT mice expressing diphtheria toxin receptor (DTR) under control of the Ccr2 locus, DT (diphtheria toxin) treatment resulted in a large depletion of tumor-associated monocytes and significant reduction of TAM numbers." (PMID 34804061, 2021). "The MCP-1/CCR2 pathway has been associated with tumour development and metastasis." (PMID 34620946, 2021).
tumor (continued). "However, anti-PD-L1 antibodies had a strong anti-tumor effect when combined with CCR2 deficiency or CCR2 inhibition." (PMID 34804061, 2021). "In the malignant microenvironment, CCL2 crosstalk with C‐C motif chemokine receptor 2 (CCR2) to modulate chemotaxis of monocytes, notably tumor‐associated monocytes, which consequently lead to the modeling of the immune microenvironment and promote cancer progression." (PMID 34525267, 2021). "However, analyzing the impact of Ccr2-deficiency on tumor sizes and vascularization led to different results." (PMID 32668709, 2020). "M-MDSC and inflammatory monocytes are recruited to tumours through a CCL1, CCL2, and CCL5-induced chemokine cascade that is propagated by cancer cells and has been found to be retained within primary tumours by CCL3 produced via CCR-2 activated mechanism in metastasis-associated macrophages." (PMID 32121014, 2020). "Hence, use of the CCR2 antagonist induced cells with more of an M1 phenotype compared to the M2 phenotype associated with MDSCs and TAMs of tumor-bearing WT mice." (PMID 33322474, 2020). "In tumor microenvironment, CCL2 interacts with C-C motif chemokine receptor 2 (CCR2) to mediate chemotaxis of monocytes and tumor associated macrophages (TAMs), which consequently contributes to the shaping of tumor microenvironment and facilitates cancer progression." (PMID 32103760, 2020). "Collectively, EVs originated from M1-polarized cells represented as a promising platform to specifically transfer the therapeutic cargo to tumor tissue; however, it was still unclear which subtype of EVs was associated with the CCR2-dominated tumor selectivity." (PMID 32550891, 2020). "Several chemokines and their receptors, in particular CCL2 and CCR2, are implicated in PCa progression, metastasis and chemoresistance, and may be expressed by tumour cells or TAMs recruited to the TIME." (PMID 32641865, 2020). "Similarly, Monocyte chemoattractant protein- 1 (MCP-1) also known as CCL2 (C-C motif chemokine ligand 2), and its receptor CCR2 (C-C chemokine receptor type 2) were linked to tumor growth and poor prognosis in colon, breast, prostate, and cervical cancer." (PMID 32355198, 2020). "Our study aimed to elucidate the role of Ccr2-deficiency within the tumor microenvironment." (PMID 32668709, 2020). "Further investigations suggested that more TAMs were infiltrated in the colon tissues of SARI deficiency mice during CAC development and MCP‐1‐mediated CCR2+ TAMs play a necessary role during SARI regulating tumour‐associated inflammation microenvironment and CAC development." (PMID 31578820, 2020). "When it comes to the Apcmin/+ mice, HFD consumption could induce gut dysbiosis and promote intestinal carcinogenesis, accompanying with activation of MCP‐1/CCR2 axis that recruited and polarized M2 tumour‐associated macrophages." (PMID 31957197, 2020). "However, Ccr2-deficiency caused a reduction of the angiogenic molecule Vegf in TAMs of the tumor-bearing hemisphere, likely due to improved nutrient and oxygen supply of stabilized vessels." (PMID 32668709, 2020). "In other tumor models, it has been described that Ccr2-deficiency led to reduced tumor sizes." (PMID 32668709, 2020). "Furthermore, we find that administration of a CCR2 antagonist or the loss of CCL2 expression in tumor cells enhances the antitumor activity of PD-1 blockade, providing a salvage alternative for residual tumors after iRFA." (PMID 31780645, 2019). "Given that chemokines can enter cells via their functionally‐active receptors, we hypothesized that fluorescently‐labelled CCL2 analogues would allow us to detect CCR2+ metastasis‐associated macrophages in tumours." (PMID 31535788, 2019). "We found a significant reduction in the percentage of mononuclear myeloid cells (monocytes and macrophages) from 63 ± 6 to 25 ± 4% (mean ± S.E.M., N = 9), and a corresponding increase in microglial cells from 18 ± 3 to 47 ± 6% in Ccr2-deficient tumour-bearing mice." (PMID 31160587, 2019).